SIRT1 (sirtuin 1)
Diseases named in the same sentence as SIRT1 in open-access papers (continued):
Sharing a sentence is not in itself a finding about the gene and the disease.
colorectal cancer (continued). "Thus, decreased miR-34a expression contributes to a miR-449a-mediated negative feedback loop to maintain low levels of miR-449a/34a and high levels of SATB2, Sirt1, HDAC1 and DNMT3a in colorectal cancer cells." (PMID 29254139, 2017). "This study discovers that SIRT1, a hub gene involved in glucolipid metabolic conversion in colorectal carcinoma (CRC), stimulates CX3CL1 secretion in CRC cells by activating FOXO1." (PMID 39783838, 2025). "It was also reported that circ-SIRT1 binds to the eukaryotic translation initiation factor 4A3 (EIF4A3) in colorectal cancer cell lines, preventing its inhibitory impact on epithelial–mesenchymal transition and encouraging the proliferation and invasion of colorectal cancer cell lines." (PMID 38003674, 2023). "In addition, SIRT-1 promotes CD24 expression by inhibiting the expression of the new tumor suppressor miR-1185-1 through histone deacetylation, thereby increasing the stemness and invasiveness of colorectal cancer cells." (PMID 35906622, 2022). "Additionally, the ubiquitin-conjugating E2 enzyme variant protein 1 (Ube2v1), an E2 member of the ubiquitin-proteasome system, promotes Ubc13-mediated ubiquitination and degradation of SIRT1, thereby inhibiting H4K16 acetylation and the transcription of autophagy-related genes in colorectal cancer." (PMID 35359990, 2022). "To further confirm whether endogenous SIRT1 and PLD isozymes can form a natural complex in colorectal cancer cells (HT119 and HT29 cells) and A549 lung adenocarcinoma cells, which express both endogenous PLD1 and PLD2, we performed coimmunoprecipitation assays." (PMID 34471223, 2021). "Also, miR-34a in 5-FU-resistant colorectal cancer (CRC) cells was found to be significantly under-expressed compared with the parental cells after 5-FU treatment and restoration of miR-34a reversed the 5-FU resistance by down-regulation of Sirt1 and E2F3." (PMID 28947999, 2017). "However, another study suggests that PUS7 also can activate the Wnt/β-catenin pathway by acting on Sirtuin 1 and PI3K/AKT/mTOR signaling pathway, indicating that PUS7 may simultaneously act on multiple downstream targets and promote colorectal cancer progression." (PMID 37420297, 2023).
metabolic syndrome (137 papers, 2008 to 2026). A cluster of metabolic risk factors for CARDIOVASCULAR DISEASES and TYPE 2 DIABETES MELLITUS. "This SIRT1-induced Nrf2 activation helps mitigate oxidative stress associated with metabolic syndrome." (PMID 40166461, 2025). "The SIRT1 rs7895833 allele A has been associated with an increased risk of metabolic syndrome in a Chinese Han population." (PMID 40507674, 2025). "Metabolic syndrome appears to cause brain mitochondrial dysfunction through a defective NAD/SIRT1 pathway." (PMID 40379890, 2025). "Another study showed that 42% of elderly patients in Brazil had variant allele G of the SIRT1 gene polymorphism, which was associated with dyslipidemia." (PMID 37892107, 2023). "In conclusion, Sirt1 rs7895833 is associated with an increased risk of metabolic syndrome in a Chinese Han population." (PMID 35365152, 2022). "An analysis of 29 severely obese patients associated with metabolic syndrome found that weight loss resulted in the activation of SIRT1, SIRT3, and SIRT6 expression in hepatic and adipose tissue." (PMID 35805129, 2022). "SIRT1 demonstrates anti-aging activity in mammals and suppresses tumors in cancer associated with aging and metabolic syndrome." (PMID 35517847, 2022). "In this study, we analyzed the association between variants in SIRT1 gene with lipodystrophy and metabolic syndrome occurrence in HIV-infected patients on HAART." (PMID 32106282, 2020). "AMPK regulates a wide range of metabolic activities and activates SIRT1 expression and its impairment involved in metabolic syndrome associated pathways." (PMID 33251210, 2020). "SIRT1 expression was also shown to prevent malignant development in a mouse model of metabolic-syndrome associated HCC." (PMID 31608282, 2019). "The downregulation of SIRT1 has been implicated as a contributing factor in metabolic disorders, inducing the metabolic syndrome and DM2." (PMID 31100876, 2019). "One model of metabolic syndrome-associated cancer examined the effects of a threefold systemic SIRT1 expression on diet-associated HCC." (PMID 31608282, 2019). "In line with this, overexpression of SIRT1 confers protection against hepatic DNA damage and associated liver cancer caused by metabolic syndrome." (PMID 29706024, 2018). "Downregulation of SIRT1 in monocytes has been associated with insulin resistance and metabolic syndrome." (PMID 25541949, 2014). "Of note, liver-specific SIRT1 transgenic mice are protected against metabolic syndrome-associated HCC." (PMID 23372727, 2013). "SIRT1 also activated the antioxidant transcription factor Nrf2, inducing the expression of cytoprotective genes to mitigate oxidative stress associated with metabolic syndrome." (PMID 40166461, 2025). "However, little is known about the association of genetic variants in the Sirt1 and Nrf2 genes with metabolic syndrome risk in a Chinese Han population." (PMID 35365152, 2022). "The probable reason might be as follows: MiR‐34a was known to regulate lipid metabolism via suppressing the expression of SIRT1; meanwhile, dyslipidemia was one of main factors causing these comorbidities." (PMID 34861059, 2022). "Interestingly, liver-specific SIRT1 transgenic mice are protected against the development of HCC associated with metabolic syndrome, and SIRT1 is crucial for the functioning of the biological clock." (PMID 34440260, 2021). "Elevated levels of the SIRT1 protein are thought to result in elongated lifespan along with reduced susceptibility to a wide variety of disease states including neurodegeneration, cancer, metabolic syndrome and autoimmune disease." (PMID 28273169, 2017). "In addition, recent studies provided direct evidence that SIRT1 can protect against carcinogenesis associated with metabolic syndrome through its anti-inflammatory effects." (PMID 24379011, 2013).
metabolic syndrome (continued). "In addition, our previous studies show that high- fat diet and Grx1 gene deletion can promote protein S-glutathionylation in mouse liver, which is related to non-alcoholic fatty liver and dyslipidemia, and S-glutathionylation of sirtuin-1 is identified as an underlying redox mechanism." (PMID 33796575, 2021). "Loss or reductions of Sirt1 activity may be associated with metabolic syndrome." (PMID 25140191, 2014). "Pharmacological modulation of this axis, using natural compounds and GLP-1 receptor agonists, has shown promise in treating metabolic syndrome, prompting interest in targeting SIRT1/AMPK signaling to manage multiple aspects of PCOS." (PMID 41471349, 2025). "The Random Forest machine learning algorithm revealed that IRS-1, p-AKT, SIRT1, and NFκB are critical predictors of metabolic syndrome severity." (PMID 40166461, 2025). "Our findings revealed that E1231-induced SIRT1 activation protects against metabolic syndrome by modulating multiple signals." (PMID 40166461, 2025). "In this study, correlation analyses provided further insights into the protective role of SIRT1 activation in metabolic syndrome." (PMID 40166461, 2025). "The strong interconnectedness between these molecules underscores the centrality of SIRT1 in coordinating a multifaceted protective response counteracting metabolic syndrome." (PMID 40166461, 2025). "Sirtuins are a family of nicotinamide adenine dinucleotide–dependent deacetylases (SIRT1–7) that are involved in the delay of aging through protective effects in vascular endothelial dysfunction, metabolic syndrome, cardiomyopathy, and tumor growth." (PMID 38333571, 2024). "AMPK and SIRT1 both regulate each other and share many common target molecules in metabolic syndrome." (PMID 37106756, 2023). "In an effort to bridge this knowledge gap, this study will analyze the influence of HIIT and RT training on SIRT1 levels among postmenopausal women diagnosed with metabolic syndrome." (PMID 37858156, 2023). "SIRT1 induces adaptive thermogenesis on WAT via the AMPK/SIRT1/PGC-1α pathway in a mouse model of metabolic syndrome induced by a high-fat high-sucrose (HFHS) diet." (PMID 37298226, 2023). "The findings point to the conclusion that regular HIIT and resistance exercise are likely to improve the status of serum levels of SIRT1 in postmenopausal women with metabolic syndrome." (PMID 37858156, 2023). "The expression of SIRT1 and SIRT6 is downregulated in lipid metabolism-related diseases, and the expression of SIRT1 is downregulated in metabolic syndrome, which exerts an adverse effect on metabolic health." (PMID 36581622, 2022). "In one rodent model of metabolic syndrome, hepatic SIRT6 was positively associated with SIRT1 and was found to improve blood lipid profiles to protect against adipose-induced oxidative stress." (PMID 35805129, 2022). "Changes in SIRT1 expression are critical in metabolic syndrome, cardiovascular diseases, cancer, and neurodegeneration." (PMID 36005430, 2022). "The concentration of resveratrol is a critical parameter and its capacity to modulate mitochondrial NAD+/NADH ratio along with SIRT1 activity can provide health benefits by activating SIRT1 downstream pathways in metabolic syndrome and age-related diseases." (PMID 34942997, 2021). "By activating PGC-1 alpha, SIRT1 can prevent metabolic syndrome by inducing lipolysis and enhancing glucose uptake with GLUT4 transporter." (PMID 34899370, 2021). "Polyphenols have been reported to possess therapeutic potential for dyslipidemia by targeting SIRT1/AMPK signaling, which plays an essential role in the regulation of hepatocyte lipid metabolism." (PMID 34884968, 2021). "Up-regulation of SIRT1 by resveratrol showed protective effects in diseases such as metabolic syndrome and neurodegenerative disorders." (PMID 33643568, 2021). "In summary, preclinical and clinical studies of Sirt1 agonists have produced contrasted results in the treatment of the metabolic syndrome." (PMID 32796716, 2020).
metabolic syndrome (continued). "Resveratrol activates Sirt1 and mimics the caloric restriction status known to be protective against the metabolic syndrome." (PMID 32796716, 2020). "SIRT1, which is an important regulator of hepatic glucose metabolism, is underexpressed in rats having metabolic syndrome." (PMID 33204398, 2020). "Numerous experimental evidence show a strong link between decreased Sirt1 and the pathological manifestations of metabolic syndrome by synergistic cellular and molecular mechanisms." (PMID 32796716, 2020). "Preclinical and clinical studies of Sirt1 agonists have produced contrasted results in the treatment of the metabolic syndrome." (PMID 32796716, 2020). "SIRT1 plays a complex role in cancer, depending on the context, and is primarily protective in various age-related diseases, such as the metabolic syndrome, neurodegeneration, and inflammation." (PMID 30463299, 2018). "Complete SIRT1 loss of function in mice induces high perinatal mortality with severe cardiac and neurological defects, while tissue specific SIRT1 knockouts aggravate diet-induced metabolic syndrome." (PMID 30463299, 2018). "Transgenic mice expressing SIRT1 at levels 2–3 fold higher than normal have been reported to be protected from developing symptoms of metabolic syndrome when animals are fed a high fat diet." (PMID 28273169, 2017). "Experiments on Res-enriched rice grains showed some benefits in improving anti-metabolic syndrome activity and inducing Sirt1, a factor relating to cell proliferation, aging, apoptosis, and metabolism." (PMID 26302213, 2015). "The SIRT1 deacetylase protects mice against the symptoms of metabolic syndrome resulting from a high fat diet." (PMID 25380034, 2014). "The present results thus suggesting that ZBH mediated amelioration of dyslipidemia is at least partially dependent upon the up-regulation of SIRT1 expression." (PMID 24759758, 2014). "Recent clinical observations revealed that SIRT1 expression in peripheral blood mononuclear cells (PBMCs) from metabolic syndrome and insulin resistant subjects was significantly reduced compared with controls." (PMID 24624081, 2014). "Resveratrol has been shown to improve mitochondrial function both in asthmatic models and metabolic syndrome models whereas resveratrol activates SIRT-1." (PMID 23840225, 2013). "While SIRT-1 is the pharmacological target in metabolic syndrome as it induces mitochondrial biogenesis by activating PGC-1α, SIRT-1 activator (SRT1720) reduced the features of allergen induced airway inflammation." (PMID 23840225, 2013). "For instance, a study demonstrated that modulation of the AMPK/SIRT1 pathway could improve outcomes in patients with metabolic syndrome‐related lung dysfunction." (PMID 39988974, 2025). "Therefore, in this study, we aimed to investigate the potential of the SIRT1 activator E1231 as a new single therapy for managing metabolic syndrome." (PMID 40166461, 2025). "Notably, SIRT1 signaling is highly reduced in the metabolic syndrome, and activation of SIRT1 can protect against metabolic syndrome-induced neurodegeneration." (PMID 40379890, 2025). "Moreover, findings of this study suggest that E1231-driven SIRT1 activation represents a novel strategy for managing metabolic syndrome." (PMID 40166461, 2025). "Notably, SIRT1 signalling is highly reduced in the metabolic syndrome and activation of SIRT1 can protect against metabolic syndrome‐induced neurodegeneration." (PMID 39644152, 2024). "In addition, this study showed the potential role of Sirt1-mediated lipid oxidation in the improvement of metabolic syndrome symptoms." (PMID 37858156, 2023). "These insightful outcomes propose that Doxercalciferol and Timiperone hold promise as viable scaffolds for developing potential SIRT1 inhibitors, with implications for tackling complex diseases such as cancer, neurodegenerative disorders, and metabolic syndromes." (PMID 38117829, 2023).
metabolic syndrome (continued). "The enlightening findings suggest that Doxercalciferol and Timiperone can be effective molecules for developing potential SIRT1 inhibitors, offering possibilities for addressing various complex diseases like cancer, neurodegenerative disorders, and metabolic syndromes." (PMID 38117829, 2023). "SIRT1 maintains also the vascular endothelial function by inhibiting the oxidative stress in vascular endothelial cells (EC), preventing or reducing the potential for the metabolic syndrome, ischaemia–reperfusion injury and inflammation." (PMID 35458574, 2022). "In contrast, NAMPT and SIRT1 exerted independent effects on diet-induced dyslipidemia." (PMID 35228549, 2022). "Similarly, glutathione adducts regulate SIRT1 activity and in turn regulate SIRT1 function in metabolic syndrome and liver disease." (PMID 35052507, 2021). "A strategy to reduce adiposity and dyslipidemia is based on the upregulation of peroxisome proliferator-activated receptor (PPARγ), peroxisome proliferator-activated receptor γ coactivator 1 α (PGC1α), and Sirtuin 1 (SIRT1)." (PMID 34574159, 2021). "SIRT1 is also increased in the aortas from metabolic syndrome rats and may be responsible for hypertension related to this metabolic disorder." (PMID 33204398, 2020). "The decreased expression of Sirt1 explains part of the consequences of fatty acid enriched diets on the metabolic syndrome, DT2, cardiovascular diseases, nonalcoholic liver disease and metabolic syndrome-associated cancers." (PMID 32796716, 2020). "We concluded that these SIRT1 polymorphisms are not predictive factors to the development of lipodystrophy and metabolic syndrome in HIV-infected individuals from Brazil." (PMID 32106282, 2020). "Our findings indicate that miR-29 controls hepatic lipogenic programs, likely in part through regulation of Ahr and Sirt1, and therefore may represent a candidate therapeutic target for metabolic disorders such as dyslipidemia." (PMID 26246194, 2015). "Moreover, studies also had demonstrated that the mRNA and protein expression of SIRT1 is reduced in obese mice and humans with dyslipidemia." (PMID 24759758, 2014). "Therefore, we can hypothesize that SIRT1 protects against metabolic syndrome through the coordinated effects on AKT, Nrf2, and NFκB signaling." (PMID 40166461, 2025). "In conclusion, carrying the GG genotype of the SIRT1 rs7895833 genetic variants in overweight subjects and rs1467568 in women could confer a possible non-risk effect against dyslipidemia." (PMID 38645486, 2024). "The present study analyzes the influence of resistance training (RT) and high-intensity interval training (HIIT) on metabolic indices and serum levels of Sirtuin1 (SIRT1) in postmenopausal women who suffer from the metabolic syndrome (MetS)." (PMID 37858156, 2023). "For instance, Sirtuin 1 (SIRT1), a histone deacetylase and an anti-aging gene, is involved in the regulation of PPAR with relevance to lipid metabolism in the adipose tissue and liver, and is associated with metabolic-related diseases, such as metabolic syndrome and cardiovascular disease." (PMID 38161971, 2023). "Thus, vitamin D and SIRT1 may play a beneficial role in the prevention and complementary treatment of metabolic syndrome, since both are key molecules in metabolic/energy sensing and in immune regulation." (PMID 37047134, 2023). "However, several lipid metabolic markers were impaired which may contribute to dyslipidemia, including two main switches for energy metabolism (sirtuin 1 and peroxisome proliferator-activated receptor-gamma coactivator-1α) and the LDL receptor." (PMID 34306160, 2021). "Moreover, the role of SIRT1 as a protector against metabolic syndrome is clear." (PMID 31608282, 2019). "Moreover, several studies have shown that Sirt1 overexpression protects animals against high fat diet (HFD)-induced glucose resistance, whereas SIRT1 down-regulation is associated with impaired glucose tolerance in individuals with metabolic syndrome and T2DM." (PMID 30513672, 2018).